IL6 (interleukin 6)
Diseases named in the same sentence as IL6 in open-access papers (continued):
Sharing a sentence is not in itself a finding about the gene and the disease.
COVID-19 (continued). "The inclusion criteria and patient settings are: Hospitalized COVID-19 patients (age ranging from 17–70) with a rising titer in biomarker profile namely IL1, IL-6, and TNFα." (PMID 35056328, 2021). "Indeed, studies have shown that intravenous administration of monoclonal IL-6 in healthy volunteers, at levels significantly exceeding the concentrations found in COVID-19, did not result in pulmonary adverse events, which further questions the importance of IL-6 in COVID-19." (PMID 33445810, 2021). "Inflammatory markers, namely, C-reactive protein (CRP), Interleukin 6 (IL-6), and erythrocyte sedimentation rate (ESR) (MMD= 36.97 mg/l, 17.37 pg/ml, 21.93 mm/hr, respectively) were raised in severe COVID-19 cases." (PMID 34760713, 2021). "A variety of inflammatory or anti-inflammatory cytokines, such as interleukin (IL)-1β, IL-6, IL-8, IL-10, and interferon (IFN)-γ, were elevated in severe COVID-19 patients." (PMID 34367188, 2021). ", and wogonin (Forsythiae Fructus) are all connected with the core target IL6, indicating that the effect of LHQW on the prevention and treatment of COVID-19 is closely related to these three active ingredients." (PMID 34731090, 2021). "CRP, D-dimer, and IL-6 are commonly elevated and LYM% diminished in patients with COVID-19 and correlate with disease severity in previous studies." (PMID 33902676, 2021). "A previous study displayed that serum levels of IL-6, IL-10, and TNF-α increase with disease severity in patients with COVID-19." (PMID 35155477, 2021). "Taken together, these data suggest a potential relationship between levels of inflammation, mediated by IL-6, levels of circulating plasminogen, as marker of fibrinolysis, and the shorter time in forming clots, as per APTT levels, typical of COVID-19 patients." (PMID 34354045, 2021). "Our present results identified obvious elevations of various cytokines in patients with severe COVID-19, including IL-1α, IL-1β, IFN-γ, TNF-α, IL-2, IL-4, IL-6, IL-10, and IL-17A." (PMID 34113636, 2021). "It has previously been shown that in severe COVID-19, SARS-CoV-2 triggers a chronic immune reaction instructed by TGFβ, which contributes to chronic upregulation of IL-6 signaling and B cell activation leading to worse COVID-19 outcomes." (PMID 34200572, 2021). "Further, regulation of levels of IL-6 and TNF-α suggest possible regulation of inflammation, as “cytokine storm” plays an important role during severe COVID-19." (PMID 34001247, 2021). "FIB-4, HA, AST, LDH, CRP, ferritin, IL-6, and ESR at admission to the hospitals (acute COVID-19 group) were higher than in the post-COVID and the control groups." (PMID 34635073, 2021). "Here, we aimed to evaluate the utility of combining IL-6 level and SARS-CoV-2 RNA load in early prediction of fatal outcomes in COVID-19 patients, including ECMO use and in-hospital death despite the use of MV." (PMID 34379684, 2021). "For this reason, treatments that suppress the immune system and inflammation such as but not limited to corticosteroids, interleukin-6 (IL-6) inhibitors, and Janus kinase (JAK) inhibitors have been studied as treatments to improve COVID-19 outcomes." (PMID 35059419, 2021). "In our observational study on 60 high viremic patients with acute COVID-19, we found that seven patients (11.66%) not only had viral shedding in urine but also presented higher inflammation markers, such as CRP, IL-6 as well as Fibrinogen." (PMID 34575171, 2021). "COVID-19 patients admitted to ICU had significantly elevated GGT activity and inflammatory markers levels (WBC count, CRP, IL-6, ferritin) than the rest of COVID-19 patients." (PMID 34680053, 2021). "Multiple studies have also demonstrated elevation of additional inflammatory markers such as IL-6, IL-8, IL-10, and TNF-α in COVID-19 patients." (PMID 33996864, 2021).
COVID-19 (continued). "It was reported significantly increased plasma levels of pro-inflammatory cytokines, including IL-1β, IL-6, IL-7, IL-8, IL-9, IL-10, interferon (IFN)-γ, and TNF-α in patients with COVID-19 than in healthy adults, but similar levels of IL-5, IL12p70, and IL-15." (PMID 34595175, 2021). "Assessment of infection-related biomarkers (CRP, ESR) and cytokine profile (IL-2R, IL-6, IL-8, IL-10, IL-1β, TNF-α, procalcitonin) on admission showed a proinflammatory state in hemodialysis patients with COVID-19." (PMID 33967613, 2021). "At baseline blood IL-1Ra, IL-5, IL-6, and TNF-alfa levels were significantly higher in COVID-19 compared to controls." (PMID 33767713, 2021). "ROC for inflammatory markers indicated the significant role of HMGB1, NLRP3, IL-6 and ACE2 in discriminating the presence of headache in patients with COVID-19." (PMID 34384355, 2021). "NET release can be triggered by various inflammatory mediators found elevated in severe COVID-19, including CRP, IL-1β, IL-6 and IL-8." (PMID 33684134, 2021). "The experimental use of DNase-1-coated melanin-like nanospheres on plasma of COVID-19 patients resulted in significant reduction of NETs and MPO activity, as well as the decrease of the cytokines IL-1b, IL-6, and TNFα, involved in the NETs pathological loop." (PMID 34445556, 2021). "IL-6 was also found to be elevated in response to SARS-CoV-2 in cell culture, animal models, and bronchoalveolar lavage fluid of COVID-19 patient samples." (PMID 33730024, 2021). "Serum Ca levels were found to correlate inversely with inflammation as assessed by white blood cell count, IL-6, and CRP levels, as well as D-dimer and procalcitonin levels, as well as organ injury in COVID-19." (PMID 33920813, 2021). "It is reported that a marked increase in inflammatory factors occurs in COVID-19, including C-reactive protein (CRP), IL-6, TNF-α, etc.." (PMID 34335279, 2021). "The relevance of the innate inflammatory response is effectively supported by the confirmation that IL6 and IL10 are the two cytokines with the highest capacity to predict a fatal course of severe COVID-19." (PMID 34829906, 2021). "Consistently, Zhao and colleagues reported that CRP, IL6, LDH and ferritin increased dramatically in COVID-19 patients, leading to disease progression." (PMID 34578138, 2021). "In this article, we will review the drugs that have indication in patients with COVID-19, including corticosteroids, antimalarials, anti-TNF, anti-IL-1, anti-IL-6, baricitinib, intravenous immunoglobulins, and colchicine." (PMID 33669218, 2021). "Although this was an uncontrolled study, it further supports the link between acute inflammatory biomarkers such as IL-6 and CRP with COVID-19 pathogenesis." (PMID 34452063, 2021). "Baricitinib is a selective JAK1 and JAK2 inhibitor and inhibits JAK1/2-dependent cytokines (e.g., IL-6 and interferon [IFN]-γ), typically involved in COVID-19 inflammation." (PMID 34356617, 2021). "The inspection of lymphoid organs of COVID-19 post-mortem cases shows that SARS-CoV-2 infects tissue-resident CD169+, ACE2+ macrophages, and subsequently stimulate IL-6 secretion." (PMID 33557330, 2021). "Similar conclusions can also be drawn from a recent study, where patients with SMD including schizophrenia who were hospitalised for severe COVID-19 had high levels of inflammatory biomarkers such as CRP, IL-6, D-dimer and ferritin, on admission." (PMID 34079487, 2021). "Higher levels of anti-SARS-CoV-2 IgA, IgM, IgG and the cytokines IL-6, IL-8 and MIP-1β at the diagnosis time were related to the severe COVID-19 outcome." (PMID 34835384, 2021). "The CD4+ TH1-lineage was similarly characterized by increased IFN- (type I and II) and interleukin (IL6, IL12, IL21) signaling in mild COVID-19." (PMID 33473155, 2021). "Overall, our study showed that high levels of immune-inflammatory markers (IL-6, IL-8, IL-10 and TNF-a) were all strong predictors of severe COVID-19 by ROC analysis." (PMID 34488665, 2021).
COVID-19 (continued). "From serum analysis, we found that the levels of IL-6 and TNF-α on admission time were higher in children with COVID-19 compared to the other groups, in line with previous studies performed on adults." (PMID 34578450, 2021). "Elevated levels of inflammatory factors such as IL-6 and CRP were observed in the paediatric patients with COVID-19." (PMID 34697118, 2021). "In this study, we derived three cytokines, IL-6, amphiregulin, and GDF-15, that were related to disease severity in COVID-19 and compared these cytokines between COVID-19 and sepsis." (PMID 35095877, 2021). "Production of proinflammatory cytokines (IL-1β, IL-6, and TNF-α) fundamental in COVID-19 pathology can directly affect platelet function and further contribute to their prothrombotic tendency, even leading to their exhaustion." (PMID 33670394, 2021). "In a retrospective cohort study, the predictive power of several reported previously identified prognosis marker [circulating lymphocytes, IL-6, lactic acid, procalcitonin, CRP (C-reactive protein), and viral load] of 142 COVID-19 patients were assessed." (PMID 35174189, 2021). "Involved cytokines seem to be different, with a more oriented IL-6, TNF, interferon and CXCL5 profile in COVID-19 and a more defined role for IL-6 and IL-10 in influenza." (PMID 34524562, 2021). "An upregulation of proinflammatory cytokines including TNF, IL-6, and IL-10 indicates the activation of a specific immune pathway probably leading to a decrease of AQP1 in patients suffering from COVID-19." (PMID 33918079, 2021). "COVID-19 patients frequently develop interleukin-6 (IL-6)-driven cytokine release syndrome (CRS), and elevated serum IL-6 correlates with respiratory failure and poor clinical outcomes." (PMID 32898168, 2020). "The Spearman correlation analysis revealed that the presence of diabetes was positively correlated with age, hs-CRP, LDH, IL-6, CD8+ cells, and severity of COVID-19 and negatively correlated with CD3+ cell counts, CD4+ cell counts, and CD4+/CD8+ ratio." (PMID 33062712, 2020). "Inhibition of the E protein IC activity significantly reduced IL-1β, IL-6, and TNF-α production, corroborating its importance in COVID-19 immunopathology." (PMID 33013759, 2020). "IL-6 and IFN-γ, which are present at high levels in the plasma of severe COVID-19 patients, are hallmarks of CRS." (PMID 32574265, 2020). "The aim of this study was to observe the association of coagulopathy (D-dimer) with cytokines [i.e., neutrophil-to-lymphocyte ratio (NLR), IL-6, and C-reactive protein (CRP)] and CT imaging in COVID-19-infected patients." (PMID 33195321, 2020). "COVID-19 patients with ARDS and MOF have elevated levels of IL-6 and C-reactive protein, which are characteristic indications of these severe conditions." (PMID 32722596, 2020). "Studies showed that increased inflammatory markers in serum of COVID-19 patients, especially CRP, procalcitonin, IL-6, and erythrocyte sedimentation rate (ESR), were positively correlated with the severity of COVID-19." (PMID 33391935, 2020). "Of the 13 mediators analyzed in serum IL-6, IL-10, monocyte-chemoattractant protein-1 (MCP-1) and interferon gamma-induced protein 10 (IP-10) were significantly increased in COVID-19 patients and tracked with disease severity." (PMID 32943497, 2020). "BTK is a key regulator of production of multiple cytokines and chemokines including TNF-α, IL-6, IL-10, and MCP-1 identified as elevated in severe COVID-19 patients." (PMID 32607505, 2020). "T cell counts were significantly reduced in COVID-19 patients, and were negatively correlated with increased serum levels of TNF, IL-6, and IL-10." (PMID 33392263, 2020). "In our study, we presented the clinical characteristics of 155 patients with COVID-19 and reported that patients had increased CRP, IL-6, hsTnI, D-dimer, and β2-MG with increased severity of the disease." (PMID 32574334, 2020).
COVID-19 (continued). "In conclusion, we obtained the worldwide case fatality rates of COVID-19 and genetic information on the IFITM3, ACE2, TMPRSS2, and IL6 genes." (PMID 33396837, 2020). "Higher levels of IL-6 and IL-10 as well as lower levels of CD4+ and CD8+ T cells found in COVID-19 patients correlated with the severity of the disease." (PMID 32944387, 2020). "In this regard, metal fume fever has been shown to produce fever, fatigue, muscle ache, cough, dyspnea, and an increase of several cytokines including IL-1β, IL-6, IL-8 and TNF-α, symptoms and cytokines that have already been described for COVID-19 patients." (PMID 32708755, 2020). "Serum cytokines including IL-2R, IL-6, IL-8, and TNF-α.were increased significantly with COVID-19 severity." (PMID 32727465, 2020). "In COVID-19, a sustained decrease in CD4+ and CD8+ T cells, especially CD8+ T cells, is observed, despite an increase in IL-6, IL-10, IL-2, IFN-γ levels, and neutrophil counts." (PMID 33335532, 2020). "Several biomarkers like IL-6, presepsin (PSP), procalcitonin (PCT), CRP, D-Dimer have showed a good function as predictor factors for the clinical evolution of COVID-19 patients (mild, severe and critical)." (PMID 33147871, 2020). "We also discovered there were higher levels and proportion of the elevation of LDH, IL-2R, IL-6, IL-8, IL-10 and TNF-α, furthermore, there were only higher levels of CRP and ferritin in the critically ill COVID-19 patients." (PMID 32788884, 2020). "Elevated levels of the chemokine MCP1 and the various cytokines (e.g., IL-6, IL-1β, TNF-⍺, IL-10 and IL-8) have been well documented in patients with severe COVID-19." (PMID 33322168, 2020). "In this article, we identify inflammatory markers (interleukin-6, D-dimer, neutrophil-to-lymphocyte ratio and hs-CRP) as predictors of COVID-19 mortality." (PMID 33392056, 2020). "Based on the crucial role of IL-6 in SARS-CoV-2-induced injury, investigation of the safety and efficacy of anti-IL-6 signaling agents is extremely important for patients with COVID-19." (PMID 33384605, 2020). "Along with IL-6, IFN-γ has been a reliable indicator of COVID-19 patient deterioration and ICU admission." (PMID 32961074, 2020). "Meanwhile, studies have reported that patients infected with COVID-19 show increased levels of pro-inflammatory neutrophils, procalcitonin, CRP and IL-6." (PMID 33192519, 2020). "Across the 23 evaluated observational studies, the association between the levels of inflammatory markers and the severity of COVID-19 and the levels of CRP, TNF-, and IL-6 was significantly high in the group with severe COVID-19 compared to the mild group." (PMID 33244370, 2020). "SARS-CoV-2 spike protein can induce IL-8, IL-6 and TNF-α secretion in monocyte-derived macrophages (MDMs) and specifically primes COVID-19 patient-derived MDMs for IL-1β production in vitro." (PMID 34192268, 2020). "COVID-19 patients had lower levels of most classical inflammatory cytokines (G-CSF, CCL20, IL-1β, IL-2, IL-6, IL-8, IL-15, TNF-α, TGF-β), but higher plasma concentrations of CXCL10, GM-CSF and CCL5, compared to non-COVID-19 patients." (PMID 33272291, 2020). "Naringenin has been used in experimental models to regulate the production of IL-6 and TNF, cytokines that are increased in COVID-19 and further increased in severe cases." (PMID 33101291, 2020). "A prior study found that the number of T cells was drastically decreased, while the level of TNF, IL6, and IL10 were significantly increased in severe COVID-19 patients compared to healthy control." (PMID 33362771, 2020). "Anti-IL-6, IL-1RA and anti-TNF-α agents are already being investigated for COVID-19 treatment and are relevant to neutrophils, which express the requisite cytokine receptors." (PMID 32943497, 2020). "A study that evaluated eight critically ill Chinese pediatric COVID-19 patients treated in the ICU, with ages ranging from 2 months to 15 years, reported increased levels of IL-6, IL-10, and IFN-γ among other laboratory findings." (PMID 32612617, 2020).
COVID-19 (continued). "IL-6-producing CD14+ CD16+ inflammatory monocytes are significantly high; therefore, the rationale for using tocilizumab has been used in COVID-19 patients." (PMID 33059757, 2020). "The binding of IL-6 and widely expressed sIL-6R is likely to fuel the hyperinflammation and be partially responsible for severe ARDS and multiorgan failure in COVID-19." (PMID 33584679, 2020). "Multiple clinical trials targeting inflammatory mediators including IL-1, IL-6, TNF-α, GM-CSF, M-CSF, IFN-γ, JAK1/JAK3, CCR2, CCR5, and complement C3/C5 are underway to treat COVID-19 patients [summarized in reference]." (PMID 32766256, 2020). "There are higher levels of inflammatory factors, including IL-2, IL-4, IL-6, IL-10, TNF-α, and IFN-γ, found in COVID-19 patients than in healthy people." (PMID 32985562, 2020). "Patients with severe or fatal COVID-19 showed significantly higher levels of inflammatory factors, such as CRP, interleukin-6 (IL-6), interleukin-2 (IL-2) and interleukin-7 (IL-7)." (PMID 32719804, 2020). "Various agents including but not limited to anti-IL-6 monoclonal antibodies and JAK inhibitors are presently under investigation to address potential components of immune dysregulation in COVID-19." (PMID 32664919, 2020). "The serum levels of IL-6, MCP-1, and IL-10 in the severe COVID-19 patients were all relatively lower than the corresponding levels in our three cohorts of CRS patients (sepsis, ARDS, and burns)." (PMID 32826331, 2020). "Ki-67 expression strongly correlated with CRP levels, and with systemic levels of the cytokines IL-6, MCP-1, IP-10 and IL-10, cytokines that were enhanced in COVID-19 patients and tracked with severity." (PMID 32943497, 2020). "It is believed that a large number of COVID-19 patients will go on to develop pulmonary fibrosis, and that these changes are mediated by a number of cytokines including TGF- ß, IL-1, IL-6, and TNF-α." (PMID 33082935, 2020). "In the two cases of severe COVID-19, the levels of CRP, PCT, serum ferritin, IL-6, and IL-10 were significantly increased, whereas the numbers of CD3+, CD4+, CD8+ T lymphocytes, and CD16 + CD56 natural killer cells were decreased." (PMID 32574284, 2020). "Being a monoclonal antibody directed against IL-6, TCZ is thought to dampen the immune response and potentially reduce the adverse outcomes related to COVID-19." (PMID 32784192, 2020). "Dental pulp stem cells exerted similar effects on the levels of IL-6 and GM-CSF in culture supernatants by resting vs. CD3/CD28-stimulated PBMCs from COVID-19 patients: up-regulation." (PMID 33634100, 2020). "Data from COVID-19 patients and a ferret model reveal low levels of IFN with contrastingly high levels of IL-6 and a strong chemokine response, suggesting a similar hyper-inflammatory response pattern to SARS and MERS." (PMID 32760407, 2020). "The levels of lymphocyte counts were negatively correlated with inflammatory indices—such as IL-6 and IFN-γ—as well as disease severity, which was more prominent in COVID-19 patients with comorbidities." (PMID 33232277, 2020). "IL-6 induces VEGF-A production, which promotes vascular hyper-permeability and vascular sprouting that are manifestations of the vasculopathy in COVID-19 (Section 4.3)." (PMID 32629875, 2020). "For most severe patients with COVID-19, the levels of pro-inflammatory cytokines soared in the serum, similar to that in SARS and MERS, including IL-6, IL-1β, IL-2, IL-8, IL-17, G-CSF, GM-CSF, IP10, MCP1, MIP1α, and TNF-α." (PMID 33178109, 2020). "A study found an increase in Th17 cell and inflammatory cytokines (IL2, IL6, IL10, and IFN-γ) in severe COVID-19 patients compared to mild cases." (PMID 33362771, 2020). "Positive correlations between the serum CXCL13 level and the levels of IL-6 and CXCL10 were also noted in COVID-19 patients." (PMID 32963357, 2020). "In COVID-19, prognostic factors of severe disease course include elevated CRP, IL-6, ferritin and D-dimer, lymphopenia, decreased monocyte and T cell counts." (PMID 33574819, 2020).